KIAA1958 (KIAA1958)
Synonyms: FLJ39294
Tractability: Antibody: the Human Protein Atlas places it where antibodies can reach. PROTAC: UniProt records ubiquitination sites on it; ubiquitination databases record sites on it.
Gene: Protein-coding gene on chromosome 9 (112,486,827 to 112,669,397, forward strand). Ensembl gene ENSG00000165185.
Subcellular location (Human Protein Atlas): Cytosol; Plasma membrane
Gene Ontology:
Molecular function: protein binding
Genetic constraint (gnomAD): Loss-of-function variants: 13 observed, 45.94 expected, observed/expected ratio (o/e) 0.28, 90% interval 0.18 to 0.45. The upper end of that interval is the gene's LOEUF score, 0.45, which puts it in group 1 of 6, group 1 being the genes least tolerant of losing a copy. Missense variants: 792 observed, 929.05 expected, observed/expected ratio (o/e) 0.85, 90% interval 0.8 to 0.9. Synonymous variants: 346 observed, 361.79 expected, observed/expected ratio (o/e) 0.96, 90% interval 0.88 to 1.04.
Homologues: Orthologues: chimpanzee KIAA1958 (99% identical), macaque KIAA1958 (99% identical), rabbit KIAA1958 (98% identical), mouse E130308A19Rik (97% identical), pig KIAA1958 (63% identical), dog KIAA1958 (63% identical), rat Kiaa1958 (62% identical), guinea pig KIAA1958 (62% identical), tropical clawed frog KIAA1958 (48% identical), zebrafish si:ch211-126i22.5 (32% identical). Paralogues in human: ZMYM4 (15% identical), ZMYM2 (13% identical), ZMYM3 (12% identical), ZMYM6 (10% identical), GTF2IRD1 (9% identical), THAP12 (8% identical), ZBED8 (7% identical), QRICH1 (7% identical), ZMYM1 (7% identical), SCAND3 (7% identical), ZBED11 (7% identical), ZBED5 (7% identical), and 6 more.
Diseases named in the same sentence as KIAA1958 in open-access papers:
KIAA1958 is named in the same sentence as 2 diseases in open-access papers, as found by Europe PMC text mining. Sharing a sentence is not in itself a finding about the gene and the disease. The quoted sentences say what the papers report.
asthma (1 paper, 2018). "Among NHWs, 391(7%) had childhood asthma, and GWAS identified one genome-wide significant association in KIAA1958 (rs59289606, p = 4.82 × 10− 8)." (PMID 30373671, 2018). "This GWAS identified a new variant in KIAA1958 associated with childhood asthma in NHWs." (PMID 30373671, 2018). "In the NHW childhood asthma GWAS, one SNP reached the level of genome-wide significance, rs59289606 located in the gene KIAA1958 (p = 4.82 × 10− 8)." (PMID 30373671, 2018).
childhood asthma (1 paper, 2018). "There was one novel genome-wide significant SNP associated with childhood asthma in the GWAS, rs59289606, an intron variant in the protein-coding gene KIAA1958 at locus 9q32; this SNP is imputed with Rsq 0.38, which meets our criteria for imputation quality." (PMID 30373671, 2018).